CCNE1 (cyclin E1)
Diseases named in the same sentence as CCNE1 in open-access papers (continued):
Sharing a sentence is not in itself a finding about the gene and the disease.
cancer (continued). "HBV integration also leads to elevated expression of several other cancer-related genes, including TERT, MLL4 and CCNE1." (PMID 26769853, 2016). "Compounds 2 and 6 accumulated cancer cells THP-1 and MCF-7 in G1 cell cycle phase, which was accompanied by the observed down-regulation of cyclin E1 levels." (PMID 27483236, 2016). "MiR-15a/16-1 cluster within 0.5 kb at chromosome position 13q14 target several oncogenes (including BCL2, CCNE1 and CCNB1, which also existed in the two networks), to suppress cell cycle progression and proliferation in several malignant tumors." (PMID 27966444, 2016). "On the other hand, carcinomas control this signaling cascade by using the opposite way (CDK2 and CCNE1)." (PMID 27802291, 2016). "The investigated carcinomas used the signaling cascade via increased expression of CDK2 and CCNE1 to drive cell cycle transition." (PMID 26008974, 2015). "To examine the prognostic roles of ALDH2, CCNE1 and SMAD3, we tested their protein expressions in FFPE samples of cancer and adjacent normal tissues from 103 patients with UTUC using IHC assay." (PMID 25408144, 2014). "We then dichotomized the 103 patients based on the protein expressions of ALDH2, CCNE1 and SMAD3 in cancer tissues." (PMID 25408144, 2014). "In this study, we demonstrate that miR-188 exerts anti-cancer potential via downregulating multiple G1/S related genes, including CCND1, CCND3, CCNE1, CCNA2, CDK2 and CDK4." (PMID 25304455, 2014). "Here we found several proliferation promoting genes including cyclin B1 /CCNB1/, cyclin E1 /CCNE1/ and cyclin-dependent kinase (CDK1) to be upregulated both in young and cancer samples compared to normal adult mucosa." (PMID 24098334, 2013). "Silencing of POP4, PLEKHF1, CCNE1 and TSZH3 selectively reduced cell viability in cancer cells harbouring their amplification." (PMID 22433433, 2012). "As well as identifying high frequency, differentially expressed genes, including known cancer genes such as PIK3CA and AURKA, we also used high amplitude regions to locate additional known (e.g. ERBB2 and CCNE1) and potential oncogenes." (PMID 20386695, 2010). "Our pan-cancer association analysis did not reveal enrichment of AM-1882 sensitivity with other cancer gene alterations (for example, CCNE1, RB1 or BRCA1)." (PMID 38151625, 2024). "Our analysis showed increased CCNE1 and MELTF expression in cancer." (PMID 39672307, 2024). "After an extensive literature review, there is no unified conclusion on the results of our pan-cancer analysis of CCNE1." (PMID 39591374, 2024). "This suggests that unlike in normal cells where CDK4/6 can rapidly compensate for pharmacologic inhibition of CDK2 to drive ongoing proliferation, this is not the case in CCNE1-amplified cancers." (PMID 38047585, 2024). "Expression of innate immune system markers (APOBEC3A/B), DNA repair genes (BRCA1, BRCA2, PALB2, RAD51), cell cycle genes (CCNA2 and CCNE1), a cell proliferation gene (MELTF), and a T-cell regulator (Treg) marker (FOXP3) was elevated in cancer compared to precancer and controls." (PMID 39672307, 2024).
cancer (continued). "The increased stimulation of CCNE1 and MELTF by HPV16 could explain why individuals with HPV16-positive precancer are more likely to progress to cancer than individuals with HPV31-positive precancer." (PMID 39672307, 2024). "Known cancer genes such as the telomerase reverse transcriptase (TERT), mixed-lineage leukemia 4 (MLL4), and Cyclin E1 (CCNE1) are preferential integration sites in HCC and about one-third of the genes recurrently targeted by HBV integration are cancer-related genes." (PMID 37927464, 2023). "Subsequently, we explored the relationships between CCNE1 and ICP expression in various cancers." (PMID 36964635, 2023). "Importantly both CCNE1 and MYBL2 play important roles in promoting cell proliferation, an important cancer cell trait." (PMID 36803948, 2023). "Moreover, focal CNA amplifications encompassed genomic peaks that harbored canonical cancer genes including those found at HPV-integrated hotspots (MYC, MYCN, MYCL, SOX2, NR4A2, and ANKRD12), and others (CCNE1, SMAD2, BCL2L1, and GNAS)." (PMID 36216793, 2022). "Interestingly, in small sets of patients with HCC, AAV showed insertional oncogenic mutagenesis similar to HBV, with a common hot spot of viral insertion within TERT, CCNE1, and CCNA2 cancer driver genes, leading to their overexpression." (PMID 36316711, 2022). "Other cancer amplified genes that also significantly increase ARE reporter activity are MYC (a previously known gene to exert post-transcriptional effect), MYCN, CCND1, CCNE1, SKP2, and NOTCH2." (PMID 34535639, 2021). "Cyclin E1 is a cell cycle regulatory protein that activates cyclin-dependent kinase 2 (CDK2), and whose gain can promote both increased proliferation and genomic instability in cancer cells, and is frequently elevated in BLBC10." (PMID 34465787, 2021). "Moreover, SNHG12 was also reported to be involved in the tumorigenesis of other cancers by interacting with miR-129-5p/WWP1, miR-195/CCNE1, miR-125-5p/MDM4, miR-326/E2F1, and miR-15a-5p/SALL4 axes." (PMID 33294456, 2020). "Furthermore, four key genes highly involved in ‘pathways in cancer,’ BIRC5, E2F1, CCNE1 and CDKN2A, were bioinformatically validated and selected out for further diagnostic and prognostic tests." (PMID 28316892, 2017). "By contrast, within these same cancer types, amplification of a chromosomal region around C17orf63 in tumors lacking amplification of CCNE1 was observed in a subgroup that contained a higher proportion of CIMP+ than CIMP− labels." (PMID 25960768, 2015). "However, miR-497 can also attenuate the malignancy of cancers by regulating other targets, such as TARBP2, DICER, BCL2, CCND1, CCNE1, CDC25A, CCND3, CDK4." (PMID 24667580, 2014). "CDK inhibitors may be a therapeutic option for cyclin E1-dependent HGSOC, including CCNE1-amplified cancers." (PMID 24624361, 2014). "The 19q12 amplicon may harbour more than a single 'driver', given that expression of POP4, PLEKHF1, CCNE1 and TSZH3 is required for the survival of cancer cells displaying their amplification." (PMID 22433433, 2012).
cancer (continued). "The effects of cyclin-dependent kinase 2 (CDK2) silencing and chemical inhibition were tested in cancer cells with and without CCNE1 amplification." (PMID 22433433, 2012). "siRNA-mediated silencing of CCNE1 had a significantly greater effect on the survival of cancer cells harbouring CCNE1 amplification than in those lacking its amplification." (PMID 22433433, 2012). "In BET bromodomain inhibitor JQ1‐resistance HCT116 cells, which showed high resistance to various anti‐cancer drugs, including cisplatin, TNIK (TRAF2 and NCK‐interacting protein kinase) was a regulator of Wnt/β‐catenin signaling and transactivate cyclin D1 (CCND1) and cyclin E1 (CCNE1)." (PMID 36408691, 2023). "Here, we performed further analyses and characterization of HBV integrations identified by our recently reported VIcaller platform in recurrent or known HCC genes (such as TERT, MLL4, and CCNE1) as well as non-recurrent cancer-related genes (such as CSMD2, NKD2, and RHOU)." (PMID 33557409, 2021). "Importantly, aberrant P27 accumulation is associated with chromosome instability (CIN; ongoing changes in chromosome numbers) and mitotic defects, whereas aberrant Cyclin E1 and c-MYC turnover lead to cell cycle and apoptotic defects that promote cancer development and progression." (PMID 35008511, 2021). "The current study builds upon that model by showing that reduced degradation of Cyclin E1 stemming from a diminished expression of SCF complex components, namely SKP1 and CUL1, is an additional mechanism by which Cyclin E1 levels may increase in cancer cells." (PMID 33731859, 2021). "CCNE1 and SAA1 have not been previously implicated in RCC, but are implicated in other cancers." (PMID 32986937, 2020). "Importantly, we, for the first time, revealed that the protein expressions of ALDH2, CCNE1 and SMAD3 were significant and independent prognostic markers for patients with UTUC, which may facilitate the clinical management of this cancer." (PMID 25408144, 2014). "Because CCNE1 amplification induces oncogenic stress and DSBs that can lead to allelic imbalances, we assessed gross chromosomal rearrangements (GCRs) in CCNE1-amplified cell lines versus non-amplified cell lines using data from the Cancer Cell Line Encyclopedia (CCLE)." (PMID 37519629, 2023). "Finally, our findings may help explain the high prevalence of CIN in a subset of cancers lacking CCNE1 amplification, but in which SKP1, or other SCF complex members are heterozygously or homozygously lost." (PMID 32106628, 2020). "To date, there are no FDA-approved drugs for CCNE1 amplified cancers, including OVCA and EMCA, despite preclinical data showing CCNE1 amplification is targetable therapeutically." (PMID 40169546, 2025). "To date, there are no FDA-approved drugs for common CCNE1 amplified cancers, such as OVCA and EMCA, despite preclinical data showing CCNE1 amplification is targetable therapeutically." (PMID 38410486, 2024). "Using combined pan-cancer studies, moderately positive correlations of CCT2 mRNA were found with MYC, CDK2, CDK4, CCNE1 but not CCND1 (slight negative correlation)." (PMID 33996588, 2021). "Four post-treatment cancers also showed focal copy number gains of ERBB2, CCND2, TERT and CCNE1 that were absent from the pre-treatment samples." (PMID 27045317, 2016). "Thus, we have identified two types of transcripts: (a) transcripts that are not expressed in normal conditions and are gained in cancer (e.g. CIT, CCNE1) and (b) transcripts that gain an additional cancer-associated transcript (e.g. MTA3, ZFHX3)." (PMID 33499898, 2021). "Furthermore, cancer cells harbouring CCNE1 gene amplification displayed a higher sensitivity to the CDK1, CDK2 and CDK9 small molecule inhibitor AZD5438 than cancer cells lacking CCNE1 gene amplification (t-test, P = 0.019)." (PMID 22433433, 2012).
adenocarcinoma (11 papers, 2013 to 2025). A common cancer characterized by the presence of malignant glandular cells. "Finally, we observed a trend toward significant decreases in ARID1A and CDKN2A mutations across CCNE1-amplified EG adenocarcinoma." (PMID 38717153, 2024). "By contrast, ERBB2 mutations were reduced in CCNE1-amplified EG adenocarcinoma." (PMID 38717153, 2024). "At present, the genetic characteristics of MiNENs containing adenocarcinoma components have been investigated in the digestive system, and it is suggested that CCNE1 gain and FAT1 loss might promote the tumorigenesis of MiNENs partially through regulating cell cycle G1/S checkpoint signaling." (PMID 38884082, 2024). "Copy number variants (CNVs) tend to be more prevalent in HAC than in common adenocarcinomas, and CNVs in CCNE1, VSTM2B, PLEKHF1, and POP4 are only present in HAC samples." (PMID 40740864, 2025). "CIN has been linked to immune cell exclusion, and prior analysis of tumors within TCGA demonstrated that “immune-cold” CIN-type EG adenocarcinoma are enriched for CCNE1 amplifications, correlating with low CD8+ T-cell abundance." (PMID 38717153, 2024). "Our study showed that CCNE1 amplification frequently occurred in high-grade adenocarcinoma and that more than 90% of CCNE1 amplification coexisted with other genomic aberrances." (PMID 35610322, 2022). "In keeping with this notion, E47 inhibited expression of Cyclin E1 and Cyclin D1 and upregulated expression of cell-cycle inhibitor p21 in adenocarcinoma A549 and H1299 cells." (PMID 33833226, 2021). "Of these, survival was best predicted by CDK1 (p<1E-16), CD24 (p<1E-16) and CADM1 (p = 7E-12) in adenocarcinomas and by CCNE1 (p = 2.3E-09) and VEGF (p = 3.3E-10) in all NSCLC patients." (PMID 24367507, 2013). "CNA analysis revealed CNA differences in several genes in CCNE1-amplified EG adenocarcinoma." (PMID 38717153, 2024). "Moreover, immunologically “cold” esophagogastric (EG) adenocarcinoma with low T-cell abundance demonstrated enrichment of CCNE1 amplification, suggesting that CCNE1 amplification may promote immune resistance." (PMID 38717153, 2024). "The present results also exhibit that among the amplified genes, the following eight genes involved in the cell cycle were found to be amplified in more than 5% of HGSO adenocarcinoma patients: ATAD2, ASF1B, CCNE1, CDC20, CDCA8, RECQL4, RNASEH2A, and SMC4." (PMID 39199556, 2024). "Using WES data and IHC, we next assessed for common coalterations with CCNE1 amplifications and compared the molecular profiles of CCNE1-amplified and nonamplified EG adenocarcinoma." (PMID 38717153, 2024). "We observed a significant increase in CNA in FGFR3, BCL3, and IDH2 in CCNE1-amplified versus nonamplified EG adenocarcinoma." (PMID 38717153, 2024). "Overall, these findings are largely consistent with comprehensive genomic profiling from our larger real-world cohort and indicate that CCNE1-amplified EG adenocarcinoma harbors a distinct molecular landscape compared with nonamplified tumors." (PMID 38717153, 2024). "Compared with adenocarcinoma, ESCC demonstrated a narrower range of CCNE1 amplification." (PMID 38717153, 2024).
infection (9 papers, 2010 to 2022). The state of being infected such as from the introduction of a foreign agent such as serum, vaccine, antigenic substance or organism. "Similarly to what was observed in mouse cells, infection with a WT MCMV induced the expression of the E2F target genes Cyclin E1 and PCNA, and to a lower extent of Cyclin A2." (PMID 30532172, 2018). "In addition, we determined expressions of CCND1, CCND2, CCNE1 and pRb in rat hypertrophic myocardium after 2-week infection with recombinant miR-16 adenovirus." (PMID 25583328, 2015). "In cultured VSMCs, treatment with PGE1-OH or infection of Ad-EP4 also significantly upregulated the mRNA levels of genes related to cell proliferation including Ki67, Foxm1, Ccna2, Ccnb1, Ccnd1, Ccnd2, Ccne1, and CDK2." (PMID 36078128, 2022). "With the progression of infection, as indicated by NSP1 protein levels, CCNE1 protein expression increased through 3, 6, and 9 hpi and was found to be maximum during 6–9 hpi with a subsequent decrease at 12 hpi." (PMID 33679655, 2021). "CUL1 and CCNE1, two S phase target genes, whose mRNA levels were upregulated at various time points after DTMUV infection, while the mRNA levels of RBX1, SKP2 and CCNE2 were decreased at all the time points, moreover, CCNE2 was time-dependently downregulated." (PMID 32897243, 2020). "Ninety-six hours after infection, total RNA was extracted and the transcript levels for LAST, CCND1, CCNE1, CDK2, CDK4 and c-Myc were analyzed by real-time RT-PCR." (PMID 29199958, 2017). "Genes involved in cell cycle CDK4, CDK5, Cyclin E1, CKN2B, CDKN2D were down-regulated at all time-points post infection." (PMID 20828378, 2010). "In the light of our results, we infer that TRIM44 and CCNE1 are significant in triggering the EMT pathway during RV infection, a phenomenon that may be required for cell-to-cell spread of RV to expand its infection within the host." (PMID 33679655, 2021).
CNS tumors (1 paper, 2018). "Well-characterized TEAD targets in non-CNS tumors include CTGF, Cyr61, MYC, CCNE1, AREG, and EGFR44,54,55." (PMID 30275445, 2018).
gastrointestinal tumor (1 paper, 2022). "Meanwhile, in the progression of gastrointestinal tumor, the synergy between NR5A21 and β-catenin/TCF4 signaling upregulate the expression of cyclin D1, cyclin E1, and c-Myc which is the downstream targets of the canonical Wnt signaling." (PMID 35633416, 2022).
neurodegenerative disease (1 paper, 2025). A disorder of the central nervous system characterized by gradual and progressive loss of neural tissue and neurologic function. "CCNE1, associated with cell cycle regulation and implicated in neurodegenerative diseases, was reduced to simulate its dysregulation in AD." (PMID 40228177, 2025).
CCNE1 also shares sentences with these, for which no sentence is quoted: esophageal squamous cell carcinoma (3 papers); leiomyosarcoma (3); lung squamous cell carcinoma (3); lymphoma (3); skin cancer (3); Breast Invasive Carcinoma (2); endometrioid ovarian carcinoma (2); gastric tumor (2); head and neck cancer (2); liver disease (2); uterine carcinosarcoma (2); adenosquamous carcinoma (1); Adrenal tumour (1); adrenocortical cancer (1); adrenocortical tumor (1); anaplastic thyroid cancer (1); Autoimmunity (1); benign ovary tumor (1); bone osteosarcoma (1); bone tumor (1); brain cancer (1); brain tumors (1); Cachexia (1); cardiovascular disease (1); cervical adenocarcinoma (1); cervical intraepithelial neoplasia (1); cervical squamous cell carcinoma (1); clear cell carcinomas (1); clear cell renal cell carcinoma (1); colorectal tumors (1).
A further 37 diseases each share a sentence with CCNE1 in 1 paper.